HTRA2 (HtrA serine peptidase 2)
Description:
[Isoform 1]: Serine protease that shows proteolytic activity against a non-specific substrate beta-casein. Promotes apoptosis by either relieving the inhibition of BIRC proteins on caspases, leading to an increase in caspase activity; or by a BIRC inhibition-independent, caspase-independent and serine protease activity-dependent mechanism. Cleaves BIRC6 and relieves its inhibition on CASP3, CASP7 and CASP9, but it is also prone to inhibition by BIRC6. Cleaves THAP5 and promotes its degradation during apoptosis. [Isoform 2]: Seems to be proteolytically inactive.
Synonyms: OMI; PRSS25; PARK13; MGCA8
Tractability: Antibody: UniProt predicts a signal peptide or a membrane-spanning region. PROTAC: UniProt records ubiquitination sites on it; ubiquitination databases record sites on it; its protein half-life has been measured; a small molecule that binds it is known.
Target class: Enzyme; Hydrolase
Gene: Protein-coding gene on chromosome 2 (74,529,596 to 74,533,350, forward strand). Ensembl gene ENSG00000115317.
Subcellular location: Mitochondrion intermembrane space; Mitochondrion membrane; Endoplasmic reticulum (Isoform 1)
Subcellular location (Human Protein Atlas): Mitochondria
Pathways (Reactome):
Cellular responses to stimuli: Mitochondrial unfolded protein response (UPRmt)
Metabolism of proteins: Mitochondrial protein degradation
Gene Ontology:
Molecular function: identical protein binding; peptidase activity; protein binding; protein serine/threonine kinase inhibitor activity; serine-type endopeptidase activity; serine-type peptidase activity; ubiquitin ligase inhibitor activity
Biological process: cellular response to growth factor stimulus; cellular response to heat; cellular response to interferon-beta; cellular response to oxidative stress; cellular response to retinoic acid; intracellular signal transduction; intrinsic apoptotic signaling pathway in response to DNA damage; mitochondrion organization; positive regulation of apoptotic process; positive regulation of establishment of protein localization to mitochondrion; positive regulation of execution phase of apoptosis; positive regulation of extrinsic apoptotic signaling pathway in absence of ligand; protein catabolic process; proteolysis; execution phase of apoptosis; mitochondrial protein catabolic process; negative regulation of cell cycle; negative regulation of neuron apoptotic process; negative regulation of oxidative stress-induced intrinsic apoptotic signaling pathway; programmed cell death; protein autoprocessing; regulation of autophagy of mitochondrion; intrinsic apoptotic signaling pathway; negative regulation of type 2 mitophagy; neuron apoptotic process; and 1 more
Cellular component: chromatin; cytoskeleton; cytosol; endoplasmic reticulum; membrane; mitochondrial intermembrane space; mitochondrion; nucleus; serine-type endopeptidase complex; CD40 receptor complex; cytoplasmic side of plasma membrane; endoplasmic reticulum membrane; mitochondrial membrane; protein-containing complex
Genetic constraint (gnomAD): Loss-of-function variants: 24 observed, 43.38 expected, observed/expected ratio (o/e) 0.55, 90% interval 0.4 to 0.78. The upper end of that interval is the gene's LOEUF score, 0.78, which puts it in group 3 of 6, group 1 being the genes least tolerant of losing a copy. Missense variants: 466 observed, 628.57 expected, observed/expected ratio (o/e) 0.74, 90% interval 0.69 to 0.8. Synonymous variants: 245 observed, 261.76 expected, observed/expected ratio (o/e) 0.94, 90% interval 0.84 to 1.04.
Gene-disease validity (ClinGen):
ClinGen rates the evidence that HTRA2 causes each of these diseases.
3-methylglutaconic aciduria type 8 (autosomal recessive): Definitive.
Homologues: Orthologues: chimpanzee HTRA2 (99% identical), macaque HTRA2 (99% identical), rabbit HTRA2 (91% identical), dog HTRA2 (90% identical), guinea pig HTRA2 (88% identical), pig HTRA2 (88% identical), rat Htra2 (87% identical), mouse Htra2 (85% identical), tropical clawed frog HTRA2 (53% identical), zebrafish htra2-9 (53% identical), zebrafish si:dkey-271n12.1 (44% identical), Drosophila melanogaster HtrA2 (40% identical), and 18 more. Paralogues in human: HTRA1 (41% identical), HTRA3 (41% identical), HTRA4 (37% identical).
Diseases named in the same sentence as HTRA2 in open-access papers:
HTRA2 is named in the same sentence as 115 diseases in open-access papers, as found by Europe PMC text mining. Sharing a sentence is not in itself a finding about the gene and the disease. The quoted sentences say what the papers report.
Parkinson disease (43 papers, 2010 to 2024). A progressive degenerative disorder of the central nervous system characterized by loss of dopamine producing neurons in the substantia nigra and the presence of Lewy bodies in the substantia nigra and locus coeruleus. "HtrA2, a mitochondrial protease that is associated with Parkinson’s disease, is playing an important role in the cleavage of DELE1 and the activation of HRI-directed integrated stress response during mitochondrial protein import stress." (PMID 38555279, 2024). "Consistent with this protective function, deletion of HtrA2/Omi or mutations affecting its activity have been associated with neurodegeneration and Parkinson’s disease in mouse models and in patients." (PMID 37594630, 2023). "HtrA2/Omi insufficiency in mice is most often associated with early‐onset neurodegeneration and Parkinson's‐like phenotypes of mnd2 (missense mutation) mice." (PMID 35349763, 2022). "Several point mutations within the PDZ domain of the HTRA2 gene have been identified in patients with Parkinson’s disease, and these mutations are demonstrated to result in HtrA2 inactivation and mitochondrial dysfunction in vitro." (PMID 34639128, 2021). "Mice without the HtrA2 proteolytic activity due to a mutation in the Htra2 gene, exhibit muscle wasting and neurodegeneration similar to symptoms of patients suffering from Parkinson’s disease." (PMID 34639128, 2021). "Mice carrying a loss-of-function variant of HtrA2 were shown to develop Parkinson-like symptoms including neurodegeneration and mitochondrial degeneration." (PMID 33227899, 2020). "In accordance, dysfunction of HTRA2 protein activity is also associated with other neurodegenerative diseases, such as Parkinson’s or Alzheimer’s disease and represents an interesting target in cancer therapy." (PMID 31443184, 2019). "Here, we report that the Parkinson’s disease-associated mitochondrial serine protease HtrA2 restricts the activation of ASC-dependent NLRP3 and AIM2 inflammasomes, in a protease activity-dependent manner." (PMID 29855523, 2018). "Researchers have shown that in both humans and animals, the loss of function of PINK1 along with HTRA2 causes Parkinsonism." (PMID 30108499, 2018). "This being so, cytopathology caused by genetic loss or reduction of HTRA2 activity constitutes a mitochondrial disease and as such has provided some of the evidence that Parkinson’s disease involves mitochondrial defects." (PMID 30013019, 2018). "In adults, variants in HTRA2 have been associated with development of tremor and Parkinson’s disease (PD)." (PMID 27696117, 2017). "Loss-of-function mutations in the gene encoding HTRA2 were found associated with Parkinson’s disease in different populations." (PMID 25531304, 2014). "Deletion of HtrA2/Omi or mutations affecting its activity have been associated with neurodegeneration and Parkinson’s disease in mouse models and patients." (PMID 24090154, 2013). "Polymorphisms in Htra2 are associated with Parkinson disease and neuronal degeneration; the Htra2 knockout mouse has severe neuronal degeneration." (PMID 20577653, 2010). "This view is further supported by the experimental observation that mutations in the HTRA2 gene cause hereditary tremors which can progress into Parkinson’s disease as well as that mice carrying a loss-of-function variant of HtrA2 develop Parkinson-like symptoms." (PMID 38816423, 2024). "Attenuated HTRA2 activity may lead to neuronal cell death, altered chaperon activity and autophagy and has been linked to Parkinson’s disease." (PMID 36862688, 2023). "Although the malfunction of HtrA2/Omi leads to Parkinson’s disease (PD), the underlying mechanism has remained unknown." (PMID 32210343, 2020). "In addition, identified mutations in the HTRA2 gene cause hereditary tremors in humans which can progress into Parkinson’s disease." (PMID 33227899, 2020). "A mutation of the HtrA2 gene is associated with Parkinson’s disease." (PMID 29755410, 2018).
Parkinson disease (continued). "HTRA2 has already been nominated as PARK13 which may cause Parkinson's disease, though there are still discrepancies among these results." (PMID 28243480, 2017). "HTRA2 exonic variant might be rare among Chinese Parkinson's disease and essential tremor patients with family history, and HTRA2 may not be the cause of familial Parkinson's disease and essential tremor in China." (PMID 28243480, 2017). "An HTRA2 variant has very recently been associated in one family with ET and optional parkinsonism." (PMID 27881096, 2016). "However, recent studies reveal that the genetic variability in HTRA2 differs among ethnic groups and at most only constitutes a risk factor for Parkinson’s disease." (PMID 25531304, 2014). "Future studies are needed to determine whether HTRA2 mutations lead to the cerebellar pathology in Parkinson’s disease patients." (PMID 25531304, 2014). "Furthermore, HtrA2 was linked to neurodegenerative diseases, as loss-of-function mutations in HtrA2 lead to the development of Parkinson-like phenotypes in a mouse model and point mutations in HTRA2 gene in humans were identified in patients with a family history of PD31,33–35." (PMID 38555279, 2024). "TRAP1 has also been shown to interact with the mitochondrial serine protease HTRA2 in Parkinson’s disease." (PMID 35740911, 2022). "Mitochondrial dysfunction is observed in autosomal recessively inherited forms of Parkinson’s disease caused by mutations in PINK1, PARKIN, DJ-1, and (HtrA Serine Peptidase 2) HTRA2 genes." (PMID 34829705, 2021). "In patients with idiopathic Parkinson’s disease, phosphorylation of HtrA2 at Ser142 is increased, and patients with Parkinson’s disease and mutations in the PINK1 gene have been shown to have diminished levels of Ser142-phosphorylated HtrA2." (PMID 33227899, 2020). "The identification of CASP1 and HTRA2, a mitochondrial serine protease mediating apoptosis in Parkinson’s disease, also highlights the important role of caspase-dependent apoptosis in merlin-deficient Schwann cells in an in vitro model of NF2." (PMID 32848608, 2020). "HtrA2 (high-temperature requirement 2) is a human mitochondrial protease that has arole in apoptosis and Parkinson’s disease." (PMID 29022916, 2017). "Focusing on the pS-MIP, we then investigated the sensitivity of the method for the detection of a proteotypic peptide from the serine protease HtrA2/Omi, a potential biomarker for Parkinson’s disease." (PMID 26126808, 2015). "Mutations in Parkinson's disease associated genes like those encoding Parkin, PINK1 (PTEN-induced putative kinase 1), HTRA2 (high temperature requirement protein A2), and DJ-1 affect mitochondrial morphology and function and cause oxidative stress." (PMID 24288463, 2013). "In addition, HtrA2 has also been reported to co-localize within Lewy bodies and has been shown to be able to reduce the propensity of Parkinson-related α-synuclein seeding whilst also contributing to the removal of existing α-synuclein aggregates." (PMID 38816423, 2024). "HTRA2 is phosphorylated on activation of the p38 pathway, occurring in a PINK1‐dependent manner at a residue adjacent to a position found mutated in patients with Parkinson's disease." (PMID 34708890, 2021). "In addition, the proteolytic activity of HtrA2 is affected by PINK1, another protein whose dysfunction is linked to Parkinson’s disease." (PMID 33227899, 2020). "However, the survival rate of hOmi/α-Syn Drosophila was increased as much as wild type, indicating that HtrA2/Omi completely rescued the Drosophila Parkinsonism induced by α-Syn." (PMID 32210343, 2020). "To tackle the biological processes responsible for the increased numbers of structurally compromised mitochondria in the HtrA2 KO brain, we first examined mitophagy, as inactivation of autophagy has been reported to contribute to neurodegenerative diseases including Parkinson’s disease." (PMID 25531304, 2014).
Parkinson disease (continued). "In particular, Parkinson's disease-specific proteins associated with fission/fusion include PTEN-inducible kinase 1/parkin, alpha-synuclein, and HTRA2/OMI, while mutant huntingtin appears to be associated with alterations in mitochondrial fission and fusion in Huntington's disease." (PMID 23468624, 2013). "One explanation to account for the lack of dominant HTRA2 mutations in Parkinson’s disease is that HTRA2 may be indispensable for mitochondrial function." (PMID 25531304, 2014). "HTRA2, a serine protease in the intermembrane space, has important functions in mitochondrial stress signaling while its abnormal activity may contribute to the development of Parkinson’s disease." (PMID 25531304, 2014). "Interestingly, both UCH-L1 as well as HtrA2/Omi have been associated with Parkinson’s disease, although a connection to necroptosis has not been investigated so far." (PMID 24090154, 2013). "Notably, dystonia or Parkinson-related proteins are altered in the XDP MSNs proteome, including ATP1A3, COL6A3, GBA, GIGF2, HTRA2, MAP2, SNCA, and TORAIP2." (PMID 38042508, 2024). "At least 19 genetic loci for Parkinsonism have been identified to date, ten of which are autosomal dominant genes: SNCA (PARK1/PARK4), PARK3, UCHL1 (PARK5), LRRK2 (PARK8), GIGYF2 (PARK11), HTRA2 (PARK13), VPS35 (PARK17), EIF4G1 (PARK18), TMEM230 (PARK21), and CHCHD2 (PARK22)." (PMID 34356877, 2021). "HtrA2 functionally interacts with the mitochondrial protein kinase PINK1 and mouse models lacking HtrA2 develop neurological defects reminiscent of Parkinson's Disease." (PMID 26977249, 2016).
Parkinson (11 papers, 2008 to 2024). "Kaplan–Meier Survival analyses also showed that HtrA2/Omi completely rescued the Drosophila Parkinsonism." (PMID 32210343, 2020). "Mutations in HtrA2 are a susceptibility factor for PD (PARK13 locus) and loss of function models in mice display a neurodegenerative phenotype resembling parkinsonism." (PMID 18560593, 2008).
prostate carcinoma (7 papers, 2021 to 2025). A carcinoma that arises from epithelial cells of the prostate gland. "Studies have shown that HtrA2/Omi plays a role in the progression of neurodegenerative diseases, prostate cancer, and hepatocellular carcinoma." (PMID 38338855, 2024). "Many researches have indicated the involvement of HTRA2 in the pathogenesis of various cancers, like ovarian, breast, colorectal, and prostate cancers." (PMID 39600313, 2024). "Multiple reports show that HtrA2 is involved in the development of various cancers, including colorectal, breast, ovarian, and prostate cancer." (PMID 36704205, 2023). "According to the results of previous studies, higher expression of HtrA2 had been found in malignant thyroid tumors, gastric cancer, and prostate cancer, and it was predictive of poor patient outcomes." (PMID 36704205, 2023). "For instance, microarray analysis has revealed that HtrA2 is reduced in primary prostate cancer, and the reduction in metastatic cancer is even greater when compared to a normal prostate." (PMID 34639128, 2021). "Research has shown that HTRA2 expression is significantly downregulated in multiple cancers, including gastric, liver, and prostate cancers, a trend that inversely correlates with IAP overexpression and may represent a mechanism for tumor cell survival." (PMID 40722819, 2025). "A similar pattern of HtrA2 expression has been reported for prostate cancer and stomach tumour." (PMID 34639128, 2021).
breast carcinoma (6 papers, 2019 to 2025). "They found that ALDH1A1 and HTRA2 regulates CCR2‐mediated breast cancer cell growth and cellular invasion in a CCL2/CCR2 context‐dependent manner." (PMID 34708890, 2021). "We modulated ALDH1A1 and HTRA2 expression in CCR2 deficient and breast cancer cell lines with induced or endogenous CCR2 overexpression." (PMID 31208996, 2019). "We found that ALDH1A1 and HTRA2 regulates CCR2-mediated breast cancer cell growth and cellular invasion in a CCL2/CCR2 context-dependent manner." (PMID 31208996, 2019). "Yet, modulating HTRA2 expression affected breast cancer cell invasion differently among the three cell lines." (PMID 31208996, 2019). "Similarly, serum high-temperature-required protein A2 (HtrA2) was reported as a potential biomarker for the diagnosis of breast cancer." (PMID 34656128, 2021). "However, the contributions of ALDH1A1 and HTRA2 to breast cancer cell growth and invasion may depend on a complex set of factors involving differences in CCL2/CCR2 signaling among breast cancer cell lines." (PMID 31208996, 2019). "In summary, CCL2/CCR2 chemokine signaling regulates breast cancer cell growth and invasion through increased ALDH1A1 expression and suppression of HTRA2." (PMID 31208996, 2019). "To examine how HTRA2 functioned in a breast cancer cell line with high levels of endogenous CCR2, we overexpressed HTRA2 in parental DCIS.com cells." (PMID 31208996, 2019). "Using 3D cell culture and transwell invasion systems, we report that CCL2/CCR2 signaling regulates breast cancer cell growth and invasion in part by enhancing ALDH1A1 expression and suppressing HTRA2 expression." (PMID 31208996, 2019). "Previous studies showed that HTRA2, a pro-apoptotic mitochondrial serine protease inversely corresponded to CCR2 expression in breast cancer." (PMID 31208996, 2019). "Our studies indicate that HTRA2 is important in CCL2/CCR2-mediated breast cancer cell growth and invasion, but not apoptosis." (PMID 31208996, 2019). "Pathologically elevated EpCAM expression orchestrates a coordinated oncogenic program involving HtrA2 downregulation-mediated apoptosis resistance, PD-L1 upregulation, Treg recruitment, and CD8+ T cell functional impairment, collectively facilitating immune evasion in breast carcinoma." (PMID 40508038, 2025). "Modulating HTRA2 expression in CCR2-H SUM225, CCR2-KO and parental DCIS.com cells led to changes in spheroid size and PCNA expression, indicating that HTRA2 exerts important effects on breast cancer cell growth regardless of cell line or CCR2 status." (PMID 31208996, 2019).
Alzheimer disease (5 papers, 2019 to 2025). A progressive, neurodegenerative disease characterized by loss of function and death of nerve cells in several areas of the brain leading to loss of cognitive function such as memory and language. "The PDZ serine protease HTRA1 degrades fibrillar tau, which is associated with Alzheimer’s disease, and inactivating mutations to mitochondrial HTRA2 are implicated in PD." (PMID 38499535, 2024). "Moreover, we found that HTRA2 expression decreased in the brains of Alzheimer’s disease patients, frontotemporal lobar degeneration with ubiquitin inclusions patients, and tauopathy model mice." (PMID 39794315, 2025). "Interestingly, the HTRA2 protein activity was found be increased in the brain tissues of Alzheimer’s disease (AD) patients, and is supposed to promote neuroprotection by enhancing autophagic processes." (PMID 34440217, 2021). "OMI/HTRA2 protease function might also have a role in neuronal damage in Alzheimer’s disease (AD)." (PMID 30361890, 2019). "Few studies on the role of OMI/HTRA2 in Alzheimer’s disease (AD) are available, but none on its relationship with the cholinergic system and neurotrophic factors as well as other AD-related proteins." (PMID 30361890, 2019).